HCP5 (HLA complex P5)
Synonyms: D6S2650E; P5-1; 6S2650E
Gene: Long non-coding RNA gene on chromosome 6 (31,463,144 to 31,494,470, forward strand). Ensembl gene ENSG00000206337.
Diseases named in the same sentence as HCP5 in open-access papers:
HCP5 is named in the same sentence as 108 diseases in open-access papers, as found by Europe PMC text mining. Sharing a sentence is not in itself a finding about the gene and the disease. The quoted sentences say what the papers report.
gastric cancer (27 papers, 2018 to 2025). A primary or metastatic malignant neoplasm involving the stomach. "Studies have shown that high expression of serum human histocompatibility complex P5 (HCP5) in gastric cancer is associated with differentiation, lymph node metastasis, and neural invasion." (PMID 40296904, 2025). "The largest cluster mainly included #0 microRNA, #1 mir-126, #2 circRNA, #3 mir-204-5p, #4 incRNA hcp5, #5 advanced gastric cancer, #6 mir-494, #7 polymorphism, #8 exosomes, #9 has_circ_0006646." (PMID 38800413, 2024). "Clinically, most evidences have showed that HCP5 overexpression is associated with the clinicopathological characteristics and prognosis of various cancers, including gastric cancer, non-small cell lung cancer, renal cell carcinoma and osteosarcoma." (PMID 34923990, 2021). "The TOPORS-AS1 lncRNA and the NADH ubiquinone oxireductase subunit B6 (NDUFB6) coding gene that were associated with HCP5 in the network analysis were downregulated in gastric cancer samples." (PMID 31137555, 2019). "We found that HCP5 overexpression increased the risk of shorter overall survival in most cancers (non-small cell lung cancer, colorectal cancer, oral squamous cell carcinoma, clear cell renal cell carcinoma, gastric cancer and osteosarcoma)." (PMID 34923990, 2021). "Concurrently, Liu’s team uncovered a novel mechanism in gastric cancer where the lncRNA HCP5 regulates ferroptosis." (PMID 41304936, 2025). "Serum HCP5 is considered to be a new indicator for the early diagnosis of gastric cancer and dynamic monitoring of tumors." (PMID 40296904, 2025). "Results showed that MSC co-culture promoted LncRNA histocompatibility leukocyte antigen complex P5 (HCP5) in gastric cancer cells, resulting in stemness and therapeutic resistance." (PMID 39170516, 2024). "This study describes the characterizes of a lncRNA HCP5‐derived microprotein, HCP5‐132aa, which exhibits an onco‐promotion effect and presents a prospective therapeutic target for the treatment of gastric cancer." (PMID 39447131, 2024). "Related studies have found that down-regulation of the long non-coding RNA (lncRNA) HCP5 can restrict the proliferation, migration, and invasion of gastric cancer cells by regulating expression level of DDX21." (PMID 37988222, 2023). "LncRNA HCP5 was found to promote the stemness and chemoresistance of gastric cancer cells by driving fatty acid oxidation." (PMID 36851037, 2023). "Previous studies find that HCP5 is regarded as an oncogene via accelerating cancer cell growth, metastasis, and drug resistance in renal cell carcinoma, gastric cancer, and colorectal cancer." (PMID 36248798, 2022). "Recent studies show HCP5 promotes proliferation and contributes to cisplatin resistance in gastric cancer cells." (PMID 35810383, 2022). "Simultaneously, the expression level of serum HCP5 was detected by qRT-PCR in 98 patients with primary gastric cancer, 21 gastritis patients, 82 healthy donors, and multiple cancer types." (PMID 34222007, 2021). "Previous study has reported that the overexpression of lncRNA HCP5 was observed in gastric cancer tissues." (PMID 33371778, 2021). "Serum HCP5 can be used as a potential biomarker of non-invasive fluid biopsy, which had a unique value in the early diagnosis, development, and prognosis of gastric cancer." (PMID 34222007, 2021). "Next, clinical relevance was analyzed between HCP5 expression level in gastric cancer and patients' clinical features." (PMID 33613117, 2021). "Moreover, HCP5 expression is negatively associated with overall survival in GC patients, indicating that HCP5 is a latent prognostic factor for gastric cancer." (PMID 33613117, 2021). "An opposing conclusion was made regarding the therapeutic use of MSC-derived exosomal ncRNA and cancer, whereby expression of various lncRNAs (AGAP2-AS1 and HCP5) promoted stemness and drug resistance in breast cancer and gastric cancer, respectively." (PMID 34660740, 2021).
gastric cancer (continued). "The diagnostic efficiency of HCP5 alone was substantially higher than that of CEA and CA199, and the combined diagnosis of HCP5, CEA, and CA199 can improve the diagnostic efficiency of gastric cancer." (PMID 34222007, 2021). "The term of serum HCP5 after the operation was significantly lower than that of patients with primary gastric cancer." (PMID 34222007, 2021). "Besides this, HCP5 was prominently upregulated and acted as an oncogene in pancreatic cancer, bladder cancer, gastric cancer, and cutaneous squamous cell carcinoma." (PMID 36248798, 2022). "Previous studies find that long noncoding RNA human leukocyte antigen complex P5 (HCP5) is regarded as an oncogene via accelerating cancer cell growth, invasion, metastasis, vascularization, and drug resistance in renal cell carcinoma, gastric cancer, and colorectal cancer." (PMID 36248798, 2022). "The expression level of HCP5 in the serum of gastric cancer patients was remarkably higher than that of healthy controls, and it could distinguish gastritis patients from healthy donors." (PMID 34222007, 2021). "In short, our study showed that the increase of serum HCP5 could significantly distinguish between patients with primary gastric cancer and healthy controls, and the combined diagnosis of HCP5, CEA, and CA199 had high diagnostic efficiency." (PMID 34222007, 2021). "To verify whether the expression of serum HCP5 was related to tumor dynamic monitoring, we compared serum HCP5 in unpaired samples, including 98 patients with primary gastric cancer, 46 patients with surgical treatment, and 57 patients with tumor recurrence." (PMID 34222007, 2021). "Besides, compared with the expression levels of thyroid cancer (THCA), colorectal cancer (CRC), and breast cancer (BRCA), serum HCP5 in gastric cancer was the most specific." (PMID 34222007, 2021). "The latest research also stated that lncRNA HCP5 may be a new and promising target for the treatment of gastric cancer." (PMID 34852705, 2021). "Both MACC1 and HCP5 are expressed in gastric cancer, and their expression may be regulated by miRNAs." (PMID 31137555, 2019). "For instance, lncRNA HCP5, induced by MSCs in gastric cancer (GC), has been found to play a role in promoting stemness and chemoresistance of GC cells." (PMID 37939296, 2024). "Thus, it can be concluded that serum HCP5 may be a potential biomarker in dynamic monitoring of gastric cancer and tumor." (PMID 34222007, 2021). "In addition, HCP5 can clearly distinguish patients with gastritis and gastric cancer." (PMID 34222007, 2021). "Besides, by comparing the expression of serum HCP5 in patients with primary gastric cancer, patients undergoing surgery, and patients with postoperative recurrence, we found that serum HCP5 rebounded in patients with tumor recurrence and it had the ability to monitor tumor dynamics." (PMID 34222007, 2021). "MSCs co-culture also improves stemness and confers chemo-resistance in gastric cancer (GC) cells by inducing the expression of metabolic pathways related LncRNA histocompatibility leukocyte antigen complex P5 (HCP5) in GC cells." (PMID 34095111, 2021). "However, the biological effects and specific regulatory pathways of the role of HCP5 in gastric cancer remain unclear." (PMID 33613117, 2021). "Furthermore, HCP5 functions as a ceRNA to sponge miR-29b-3p, miR-140-5p, miR-139-5p, and miR-186-5p, which consequently promotes cell growth, metastasis, invasion and epithelial–mesenchymal transition in hepatocellular carcinoma, clear cell renal cell carcinoma, colorectal cancer, or gastric cancer." (PMID 34923990, 2021). "Only 6 (H19, HCP5, LINC00511, MALAT1, OIP5-AS1 and RP11-618G20.1) out of 79 lncRNAs were significantly up-regulated in gastric cancer tissues compared to normal controls." (PMID 32742441, 2020).
gastric cancer (continued). "Besides, large serum samples of gastric cancer detected by qRT-PCR showed that HCP5 could not only significantly distinguish between GC patients and healthy donors, but also could distinguish GC patients from gastritis patients well." (PMID 34222007, 2021). "There have been no reports of regulation between miRNAs and HCP5 until now, but our results suggest that the expression of HCP5 may be regulated by miRNAs in gastric cancer." (PMID 29992774, 2018).
glioma (21 papers, 2017 to 2024). A benign or malignant brain and spinal cord tumor that arises from glial cells (astrocytes, oligodendrocytes, ependymal cells). "HCP5 is a well-known lncRNA that is associated with numerous cancers, such as human triple-negative breast cancer, glioma, and hepatitis C virus-associated hepatocellular carcinoma." (PMID 33439936, 2021). "This direct interaction between microRNA and lncRNA regulated the response of glioma cells to ionizing radiation by interfering with cellular senescence as the knockdown of lncRNA HCP5 inhibited cell proliferation and enhanced radiosensitivity in gliomas." (PMID 38419943, 2024). "In the study of glioma, HCP5 was found to be correlated with the migration and proliferation of glioma cells." (PMID 38071681, 2024). "Several studies have demonstrated that the expression of lncRNA HCP5 is upregulated in glioma, cervical cancer, and follicular thyroid cancer, but decreased in ovarian cancer." (PMID 36980766, 2023). "The expression of lncRNA HLA complex P5 (HCP5) was positively correlated with glioma malignancy and HCP5 knockdown promoted cellular senescence and sensitivity to radiation and inhibited cell proliferation by sponging miR-128." (PMID 34202078, 2021). "Previous research has considered HCP5 to be an oncogene in cervical cancer 26, glioma 27 and follicular thyroid carcinoma 28, while HCP5 downregulation was also found in malignancy like nasopharyngeal carcinoma 29, lung adenocarcinoma 30 and ovarian cancer." (PMID 33613117, 2021). "Researches have indicated that HCP5 acted as an oncogene in glioma, and the expression of HCP5 increased with the level of grade of glioma." (PMID 34194477, 2021). "It is also reported that knockdown of HCP5 can inhibit proliferation, cell migration, and invasion, so as to promote apoptosis of glioma cells." (PMID 34194477, 2021). "HCP5 (HLA complex P5) is dysregulated in a wide variety of cancers and diseases such as osteosarcoma, cervical cancer, and glioma as well as psoriasis and kawasaki disease." (PMID 32760219, 2020). "In the basal subtype of breast cancer, HCP5 was bound to miRNA-155, affecting cell proliferation and aggressiveness of tumor, whereas in glioma, malignancy was shown to be regulated by an HCP5-miRNA-139-RUNX1 feedback loop." (PMID 32375397, 2020). "The “sponging” effect of HCP5 on miRNA-139 unleashed the RUNX1 expression, connecting HCP5 to glioma oncogenesis." (PMID 32375397, 2020). "HCP5 was also found upregulated in glioma tissues as well as in U87 and U251 glioblastoma cell lines." (PMID 32375397, 2020). "Oncogenic RUNX1 promoted the growth of glioma cells as well as the expression of HCP5 and its binding to the tumor suppressor miRNA-139." (PMID 32375397, 2020). "For example, HCP5 enhances the biological behaviors of glioma cells by upregulating RUNX1, while RUNX1 also activates HCP5 expression through binding to its promoter region, forming a positive feedback loop." (PMID 31186064, 2019). "HCP5 expression was positively correlated with the oncogenesis of a pathological grade of glioma tissues, and knockdown of HCP5 exerted tumor-suppressive effects in human glioma cells by allowing an increase in expression of the miRNA tumor suppressor miR-139." (PMID 31137555, 2019). "HCP5 also was overexpressed in lymph node metastasis of small cell lung cancer, glioma tissue, colorectal cancerous tissue, and cancers of the colon, thyroid, cervix, and breast." (PMID 31137555, 2019). "Inhibiting the expression of HCP5 could induce the cell apoptosis and reduce the proliferation, migration, and invasion of glioma cells." (PMID 39279987, 2022). "Studies have shown that the level of HCP5 is increased in glioma tissues and U87 and U251 cells." (PMID 35602292, 2022). "HCP5 could act as a tumor suppressor by modulating malignant phenotypes of glioma cells through binding to microRNA-139." (PMID 39279987, 2022).
glioma (continued). "Significantly, HCP5 was found to be overexpressed in lymph node metastasis of different types of cancer including small cell lung cancer, colorectal cancerous tissue, glioma tissue, and prostate cancer." (PMID 32375397, 2020). "Moreover, overexpression of HCP5 and Linc00152 facilitates the malignant biological behaviors of glioma cells." (PMID 31186064, 2019). "The malignant behavior of glioma cells in the brain appears to be regulated by an HCP5–miR-139–RUNX1 feedback loop, whereby RUNX1 increased the promoter activities and expression of HCP5 that binds to the tumor suppressor miRNA-139 (miR-139) and, therefore, acts as an oncogene." (PMID 31137555, 2019). "The HCP5 promoter also contains a 22 nt RUNX1 sequence that might contribute to the interaction between the HCP5 transcript and the Runx transcription factor in glioma and in the monocytes of HIV patients." (PMID 31137555, 2019). "Thus, it was concluded that HCP5 promotes cell proliferation, cell migration, and invasion (motility) and inhibits apoptosis, as do many other lncRNAs participating in glioma phenotypes." (PMID 31137555, 2019). "In addition, they found that HCP5 regulated the glioma cells malignant proliferation through binding to miR-139 by up-regulating RUNX1." (PMID 30364292, 2018). "The importance of the prognostic effect of 3 feature lncRNAs in glioma patients ranged from high to low: WDFY3-AS2, HCP5, and SNHG16." (PMID 39279987, 2022). "HCP5 up-regulates runt-related transcription factor 1 (RUNX1) by acting as miR-139 sponge to promote astrocyte elevated gene-1 (AEG-1) expression, which is involved in several oncogenic effects in glioma cells." (PMID 33439936, 2021). "Furthermore, lncRNA HCP5 sponge miR-139 to up-regulate RUNX1, and then RUNX1 feedback promoted HCP5 expression by binding to HCP5 promoters, creating a HCP5/miR-139/RUNX1 positive feedback loop to regulate the malignant behavior of glioma cells." (PMID 29458374, 2018).
autoimmune disease (14 papers, 2013 to 2025). A disorder resulting from loss of function or tissue destruction of an organ or multiple organs, arising from humoral or cellular immune responses of the individual to their own tissue constituents. "HCP5 is associated with several autoimmune diseases including psoriatic arthritis, systemic lupus erythematosus, and Graves’ disease; and OIP5-AS1 was found to play a critical role in the ceRNA network of multiple sclerosis." (PMID 34603387, 2021). "Apart from HIV infection, AIDS, and abacavir hypersensitivity, the HCP5 [rs2395029] SNVs also were associated with other adverse drug reactions, autoimmune diseases, and abnormal phenotypes." (PMID 31137555, 2019). "Since its discovery in 1993, many disease association and gene expression studies have shown that HCP5 is a regulatory lncRNA involved in adaptive and innate immune responses and associated with the promotion of some autoimmune diseases and cancers." (PMID 31137555, 2019). "This is very close to the HLA complexP5 (HCP5) which is associated with susceptibility to autoimmune diseases." (PMID 24352087, 2013). "HCP5 (HLA complex P5) is a long non-coding RNA (lncRNA) located in the HLA I region, which involved innate and adaptive immune response and association with the occurrence of certain autoimmune diseases and cancer." (PMID 33446692, 2021). "Further, the long noncoding RNA gene HCP5, located within the HLA class I region, is involved in immunity and plays a role in autoimmune diseases and cancer." (PMID 40977520, 2025). "Our Bayesian colocalization analysis revealed five genes, including GTF2H4, FLOT1, HCP5, immediate early response 3 (IER3), and serine/threonine kinase 19 (STK19), that were identified as having a shared variant with autoimmune diseases (PP.H4 > 0.8)." (PMID 40599891, 2025). "HCP5 is the gene with the lowest logFC methylation values, it maps on the 6p chromosome, and it has been shown to have a role in autoimmune diseases as well as promoting proliferation and metastasis in different cancers." (PMID 37958591, 2023). "The HCP5 gene is located in the major histocompatibility complex class I region and codes for a long noncoding RNA involved in many autoimmune diseases." (PMID 35887591, 2022). "Altogether, these results revealed that HCP5 main participate in the biological mechanism of cancer and autoimmune disease." (PMID 34923990, 2021). "HCP5 gene SNVs and neighboring upstream and downstream SNVs have been associated with HIV viral load, HPV infection, autoimmune diseases, disease relapse after transplantation, and various cancers." (PMID 31137555, 2019). "A previous study also links HCP5 to the development of certain autoimmune diseases and cancers." (PMID 39200825, 2024). "It is evident from the results and reports presented in this review that HCP5 contributes to regulating viral and autoimmune diseases and cancer, and it can be upregulated or downregulated depending on its response to various exogenous or endogenous stimulators or suppressors." (PMID 31137555, 2019). "HCP5 is closely involved in some diseases, such as chronic kidney disease, HIV infection, autoimmune diseases 42-45." (PMID 35399723, 2022). "HCP5 is a vital lncRNA between the MICA and MICB genes in the MHC I region and is involved in many autoimmune diseases, including malignant tumors." (PMID 35571053, 2022). "The source gene of lnc-HCP5 is located between MICA and MICB genes, which regulates the activities of various immune cells such as B cells, lymphocytes and NK cells, and plays an important role in HIV, AIDS, and various autoimmune diseases." (PMID 33194692, 2020).
follicular thyroid carcinoma (14 papers, 2018 to 2023). "HLA complex P5 (HCP5) another lncRNA has been implicated in the pathogenesis of follicular thyroid carcinoma and anaplastic thyroid carcinoma by regulating the expression of tumour suppressor miR-128-3p." (PMID 33126409, 2020). "Previous study suggested that overexpression of HCP5 promoted the proliferative, migratory, invasive, and angiogenic capabilities of follicular thyroid carcinoma cells." (PMID 33371778, 2021). "Briefly elaborated as follows:In thyroid carcinoma, HCP5 promoted the proliferation, migration, invasiveness and angiogenic ability of follicular thyroid carcinoma cells via sponging miR-22-3p, miR-186-5p, miR-216a-5p and activating ST6GAL2." (PMID 34923990, 2021). "The long non-coding RNA-HLA complex P5 (HCP5) has been found to be overexpressed in follicular thyroid carcinoma, which functions as a competing endogenous RNA and acts as a sponge for several miRNAs." (PMID 31721901, 2019). "The long non-coding RNA–HLA complex P5 (HCP5) has been found to be overexpressed in follicular thyroid carcinoma and functions as a sponge for miR-22-3p, miR-186-5p and miR-216a-5p, which activates ST6GAL2 to promote disease progression." (PMID 31065463, 2019). "In follicular thyroid carcinoma, up-regulated ST6GAL2 in advanced cells and its co-expression with LncRNA HCP5 was strongly associated to cell proliferation, migration, invasiveness and angiogenesis." (PMID 30704472, 2019). "lncRNA HCP5 is overexpressed in follicular thyroid carcinoma and could induce tumor development." (PMID 35602292, 2022).